INS (insulin)
Diseases named in the same sentence as INS in open-access papers (continued):
Sharing a sentence is not in itself a finding about the gene and the disease.
morbid obesity (continued). "Skin tags are associated with an insulin resistant phenotype but studies in White Europeans with morbid obesity are lacking." (PMID 32178726, 2020). "Additionally, a previous study in patients with morbid obesity and T2D had decreased serum kisspeptin levels and HbA1c together with decreased insulin secretion and increased insulin sensitivity following Roux-en-Y gastric bypass surgery." (PMID 33224197, 2020). "Thus, it is not surprising that we did not observe any alternations in FABP4 expression in different depots of adipose tissue, since examined patients with morbid obesity were sensitive to insulin." (PMID 29335416, 2018). "To summarise, circulating RBP4 may play a major role in lipid metabolism in morbid obesity in which it is associated with an increase in triglyceride levels and contributes to the formation of small HDL, independently of insulin-resistant state." (PMID 24223837, 2013). "Although further evidence needs to be accumulated, including long-term outcomes, laparoscopic sleeve gastrectomy may provide an effective treatment for patients with morbid obesity and T1DM for body weight loss, improvement in HbA1c level, and insulin dose reduction." (PMID 33409743, 2021). "In a recent review of studies on children and adolescents with morbid obesity, cardiovascular risk parameters were only investigated in three of the included studies; the results demonstrated that children achieved positive effects on cardiometabolic risk markers (LDL, TG, and insulin sensitivity)." (PMID 30634657, 2019). "(I) KCNN1: The lipotoxicity in morbid obesity can gradually impair insulin action in the liver and muscle, aggravating insulin resistance, and Ye, J proposed an energy-based concept of insulin resistance, in which insulin resistance is a result of energy surplus in cells." (PMID 29132311, 2017). "In subjects with morbid obesity, decreased AT SIRT1 was observed in the insulin resistant vs. insulin sensitive group." (PMID 29417372, 2018). "Similar to adiponectin, apelin also improves insulin sensitivity by increasing Akt phosphorylation and glucose uptake via the AMPK pathway, with studies reporting higher apelin concentrations in insulin-resistant and/or individuals with morbid obesity and T2D." (PMID 41376626, 2025). "In addition, AUC for insulin and glucose following MMTT were both significantly greater in the participants with morbid obesity." (PMID 35757406, 2022). "Our case shows the possible usefulness of bariatric surgery for the treatment of patients with morbid obesity and T1DM, without endogenous insulin, to achieve postoperative weight loss and to improve glycemic control 1 year after surgery." (PMID 33409743, 2021). "As in previous studies, we found decreased levels of IRS1 VAT from patients with morbid obesity, independent of the insulin-resistant state, with metformin slightly increasing IRS1 expression." (PMID 32806641, 2020). "In subjects with morbid obesity and T2D, GLP-1R expression in AT is of limited value to predict incretin response and does not play a role in metabolic outcomes such as insulin sensitivity improvement, T2D remission and weight loss after bariatric surgery." (PMID 31000783, 2019). "In this case report, we describe the effectiveness of laparoscopic sleeve gastrectomy (LSG), by reducing the size of the stomach, in a patient with morbid obesity and T1DM, without endogenous insulin, achieving weight loss, a marked reduction in insulin requirement, and improved glycemic control." (PMID 33409743, 2021). "In addition, the associations between FGF21 and several insulin-related profiles, including C-peptide, insulin, and HOMA-IR, after LSG were not noted in the patients with morbid obesity before surgery." (PMID 32210348, 2020).
morbid obesity (continued). "When the Cyp4x1-knock out mice were tested with glucose or insulin challenges at 20 weeks of age we found no significant impairment of glucose homeostasis, so the phenotype is one of increased adiposity rather than of morbid obesity." (PMID 29227996, 2017). "In subjects with morbid obesity, ORM correlated positively with fasting insulin and HOMA-IR in men but not in women." (PMID 35103244, 2022).
Cachexia (55 papers, 1989 to 2026). Severe weight loss, wasting of muscle, loss of appetite, and general debility related to a chronic disease. "Insulin is an anabolic factor that counteracts protein degradation and promotes protein synthesis in muscles, so insulin insensitivity further aggravates muscle loss with cachexia." (PMID 35406586, 2022). "We also demonstrated that insulin return from the lifetime peak levels contributes to age-dependent bone mass loss and cachexia-like condition, supported by the results of the intervention study in old rats." (PMID 33744845, 2021). "Nevertheless, an important target deserving further investigation is the circadian rhythm alteration which has been proposed to foster altered insulin sensitivity, a hallmark of cachexia." (PMID 33202621, 2020). "Cachexia is a multisystem syndrome characterized by weight loss, anorexia, loss of muscle mass, systemic inflammation, insulin resistance, and functional decline." (PMID 30482179, 2018). "In addition, only insulin was associated with improvement in overall survival among cancer patients with cachexia." (PMID 30482179, 2018). "In addition to weight loss, patients with cancer cachexia suffer from multisystem syndrome characterized by anorexia, loss of muscle mass, systemic inflammation, insulin resistance, and functional decline." (PMID 30482179, 2018). "This information may include routine chemistry measurements, such as glucose and insulin levels, nutritional and dietary factors, along with weight status (e.g., recent weight loss from cachexia)." (PMID 24958258, 2013). "To assess whether IMD-dependent insulin signaling decrease in MTs was involved in the different phenotypes associated with the wasting syndrome, we probe whether expressing a constitutive active form of PI3K (PI3KCAAX) in MT principal cells could rescue the Ecc-mediated phenotypes." (PMID 32839462, 2020). "Improves adipose mass and insulin sensitivity in Walker-256 cachexia; systems-level remodeling noted in tumor-bearing mice." (PMID 41476922, 2025). "Together, these data demonstrate that dietary supplementation of nicotinamide or lipids can potentially improve outcomes in cachexia through the modulation of insulin signalling, lipid metabolism or beta-oxidation." (PMID 38429578, 2024). "In addition, skeletal muscle loss often leads to increased intramuscular fat infiltration, which in turn leads to insulin resistance, muscle strength loss and motor dysfunction, which can lead to systolic dysfunction and metabolic and endocrine abnormalities, and ultimately lead to cancer cachexia." (PMID 39027658, 2024). "Utilising a Drosophila model of cachexia, we have demonstrated that muscle wasting in cachexia is mediated by two main mechanisms: insulin signalling via FOXO and mitochondrial beta-oxidation." (PMID 38429578, 2024). "In malaria, cachexia is explained because infection with the parasite promotes the synthesis of proinflammatory cytokines that decrease lipogenesis and increase insulin resistance, which induces gluconeogenesis and proteolysis and decreases protein synthesis." (PMID 37384220, 2023). "Using LPS-stimulated piglets to establish the model of cachexia, we quantified the concentrations of plasma markers of cachexia, such as INS, GH, COR, and GLU." (PMID 37446099, 2023). "In agreement with previously published results of cachexia patients and organisms, the INS and GH levels and the COR and GLU levels were decreased and increased, respectively." (PMID 37446099, 2023). "Together, our data indicate that the elevation of fat body insulin signalling level can improve muscle integrity in the context of cachexia." (PMID 38014610, 2023). "Hormonal signals involved in cachexia include insulin and insulin growth factor 1 (IGF-1), leptin, ghrelin, melanocortins, neuropeptide Y and growth hormone." (PMID 35326490, 2022).
Cachexia (continued). "The BCAAs (valine, leucine and isoleucine) are essential amino acids; BCAAs stimulate anabolic pathways and thus mitigate cachexia, prevent hepatic encephalopathy, lower fatigue during exercise, stimulate wound healing and promote insulin production." (PMID 34830706, 2021). "A number of trials stated that carbohydrate intake and metabolic efficiency during exercise stimulated by low dose insulin treatment (0.11±0.05 units/kg/day), resulted in increased survival in cancer cachexia patients." (PMID 32102506, 2020). "Supportive care including dietary treatment and physical exercise that can maintain energy balance, as well as increase insulin sensitivity, protein synthesis rate, and anti-oxidative enzyme activity, which is beneficial for relieving symptoms of cachexia." (PMID 31114756, 2019). "Given that the lower body weight in KA is considered as cachexia, it is still more interesting that the improvement of insulin signalling was also sufficient to improve cachexia in KA-PTEN mice." (PMID 31616027, 2019). "Insulin is an important hormone and plays a prominent role in the physiologic changes that occur in the setting of cachexia." (PMID 30975087, 2019). "From the ongoing discussion, it appears that telmisartan is beneficial in controlling cachexia as evident from the improvement in cachexia markers namely, insulin, CRP, and IL-6." (PMID 24381940, 2013). "These variations had been reported under different circumstances: during the menstrual cycle, after the administration of adrenocorticotropic hormone and insulin, with senility, and with cachexia." (PMID 24385754, 2013). "We studied the effect of food restriction, overfeeding, and normofeeding on cachexia, inflammatory and metabolic parameters, and insulin sensitivity in chronic adjuvant arthritis (AA) in rats." (PMID 20953376, 2010). "By improving insulin sensitivity, enhancing anti-catabolic signaling, and reducing systemic inflammation, rosiglitazone contributes to both metabolic stability and muscle preservation, highlighting its potential therapeutic relevance in cancer cachexia." (PMID 41476922, 2025). "Cancer-related cachexia is induced by changes of systemic metabolic environment due to elevation of inflammatory cytokines in tumor cells, hepatocytes and adipose tissue, changes of protein synthesis and degradation in skeletal muscle and insulin resistance." (PMID 38811687, 2024). "Several mechanisms have been proposed behind chemotherapy-induced cachexia, including the generation of reactive oxygen species, activation of proteases like calpain and caspases, and impaired insulin signaling." (PMID 39196610, 2024). "To determine whether the model of LPS-induced cachexia is established, we initially examined the concentrations of several blood markers of cachexia including plasma insulin (INS), growth hormone (GH), cortisol (COR), and glucagon (GLU)." (PMID 37446099, 2023). "Fat body insulin signalling has been known to modulate the overall size of the animal by altering systemic ecdysone levels and thus we considered whether the insulin signalling pathway may influence cachexia via this growth hormone." (PMID 38014610, 2023). "Next, we tested whether fat body‐specific changes in Insulin signalling influences muscle breakdown during cachexia." (PMID 38014610, 2023). "Therefore, maintaining glucose homeostasis and improving insulin sensitivity are the keys to suppressing muscle wasting in cancer cachexia." (PMID 36105371, 2022). "Insulin combined with other nutritional measures may be used to improve body reserve of patients with tumor cachexia." (PMID 36524002, 2022). "It is noteworthy that interruption of systemic insulin signaling by ImpL2, which antagonizes insulin signaling by binding to Drosophila insulin-like peptides (DILPs), and bacteria-derived PGN cause a wasting syndrome affecting fluid homeostasis, fat body and ovaries." (PMID 32839462, 2020).
Cachexia (continued). "Herein, we present the following results: 1) a TZD dose-dependent response that affects survival; 2) body weight and tumor mass evolution during cachexia progress; and 3) insulin-induced glucose uptake from isolated adipocytes at the early and final stages of cachexia." (PMID 25807446, 2015). "Although cancer-cachexia decreases plasma insulin levels, the leucine-rich diet improved the plasma insulin level in the LW group, and could serve as a stimulus for protein synthesis." (PMID 17341295, 2007). "Increased hepatic glucose production may be stimulated by an increased glucose requirement, which might explain why, apart from the increased energy expenditure, elevated plasma glucose-triggered insulin resistance and excess catabolism are also common pathological features of cancer cachexia." (PMID 36230949, 2022). "Together, these data suggest that fat body insulin and TGF‐β signalling converge to specify ECM levels in the fat body and in turn, the muscle during cachexia." (PMID 38014610, 2023). "This suggests that although muscle TGF‐β signalling is responsive to circulating insulin levels, muscle TGF‐β signalling is functionally dispensable in facilitating muscle degradation during cachexia." (PMID 38014610, 2023). "Although our data suggest that insulin and TGF‐β signalling act in a linear pathway in the fat body to facilitate cachexia, it is unclear how the tumour‐secreted proteins ImpL2 and Gbb interact with each other to facilitate the progression of cachexia." (PMID 38014610, 2023). "In the attempt to evaluate the interaction between cachexia and PGZ treatment on cell sensitivity to insulin, a glucose uptake test was done using isolated adipose cells from RPAT depot." (PMID 25807446, 2015). "This phenotype was neither accompanied with a clear reduction of the systemic lipid level nor with reduced insulin signaling, common phenotypes observed in cachexia patients and animal models." (PMID 29592890, 2018). "Findings of sex differences in cachexia severity and measures of BCAA catabolism could be related to various factors, including differences in insulin sensitivity, hormonal profile, variations in fiber type composition of muscles in males vs females, drug pharmacokinetics, and protein metabolism." (PMID 41525266, 2026). "In a randomized controlled study of patients with cachexia, compared with treatment without insulin, treatment administering a small amount of insulin daily increases metabolic efficiency during exercise by increasing the whole body fat content and significantly improves survival rate." (PMID 36105371, 2022). "Treatment with TP5 totally reverted the effect of cachexia on 2DG uptake by RPAT adipocytes, that showed no response to insulin ranging from basal to maximal (10 nM) stimulation." (PMID 25807446, 2015).
melanoma (55 papers, 2010 to 2026). A malignant, usually aggressive tumor composed of atypical, neoplastic melanocytes. "Pathway analysis further reveals that the genes in the module are enriched in some signal transduction pathways like insulin signaling pathway and chemokine signaling pathway, and also in some cancer-associated pathways like melanoma." (PMID 28389669, 2017). "Crizotinib may be used as a complementary therapy for melanoma with BRAF mutations by inhibiting the mTOR/Insulin signaling pathway." (PMID 37770477, 2023). "Therefore, the causal relationship between Insulin and the risk of Melanoma requires more research." (PMID 38179409, 2023). "The top five enriched KEGG pathways were insulin signaling pathway, melanoma, peroxisome, T cell receptor signaling pathway, and vascular smooth muscle contraction." (PMID 36814485, 2023). "Insulin levels are reported to be depleted in melanoma, and systemic supplementation of insulin is shown to attenuate muscle atrophy and to reduce tumour burden." (PMID 34212132, 2021). "These responses are found to manage osteoclast differentiation, insulin signaling pathway, pulmonary barrier integrity, liver regeneration, and proliferation of malignant melanoma cells." (PMID 33081347, 2020). "Many growth factor receptors are expressed on melanoma cells including receptors for insulin and IGF-1, two key growth factors increased in obese patients." (PMID 32549336, 2020). "The role of IGF axis in human melanoma is also of considerable importance and prompted us to analyze RNA levels of insulin-IGF axis in human melanoma cells during GH-excess and GHRKD." (PMID 28223541, 2017). "For instance, it was also reported that insulin signaling negatively regulates Stat3 transcription in human melanoma cells." (PMID 29146985, 2017). "As we report here, the melanoma cells indeed appear to be in a state of heightened insulin/IGF sensitivity via abundant expression of IR, IGF1R and IGF2R as seen in all four melanoma cells in this study." (PMID 28223541, 2017). "In humans, Trib2 has been identified as a repressor of FoxO in malignant melanomas and complimentarily, FoxO represses Trib3 expression to derepress Akt and enhance insulin sensitivity in hepatocytes." (PMID 25329475, 2014). "The significant rise in the insulin released by melanoma cells might be a metabolic consequence of the oxidative stress evidenced by ROS elevation and possibly impacting metabolic function." (PMID 41596411, 2026). "Therefore, the present study aims to demonstrate the effects of insulin administered to mice with melanoma, the relationship between the tumor response and blood glycemia and the protein expression possibly involved in this mechanism." (PMID 38658239, 2024). "The 2-h Glucose and Fasting Insulin results showed no apparent causal relationship with Melanoma risk." (PMID 38179409, 2023). "In all models analyzed, there was no apparent causal relationship between Fasting Insulin and Melanoma risk." (PMID 38179409, 2023). "These include hemoglobin genes (HBB, HBG1, HBG2) in the peripheral blood-derived cell line KU812, MIA (melanoma inhibitory activity) in the melanoma-derived cell line A375 as well as insulin (Ins1, Ins2) and islet amyloid polypeptide (Iapp) in the mouse pancreatic beta cell line Beta-TC6." (PMID 28687070, 2017). "Other signaling pathways related to endocytosis, Wnt, ECM-receptor, neurotropin, Glutamatergic, insulin, protein digestion/absorption, ErbB, Gap junction, mTOR, melanoma, phosphatidylinositol, adherens junction, GnRH, Fc epsilon RI, and circadian rhythm are also significantly affected (p<0.001)." (PMID 27793049, 2016). "However, no causal relationship between fasting insulin and melanoma was found." (PMID 38179409, 2023).